MITF (melanocyte inducing transcription factor)
Diseases named in the same sentence as MITF in open-access papers (continued):
Sharing a sentence is not in itself a finding about the gene and the disease.
melanoma (continued). "Recently, several lines of evidence indicate a pivotal role for the transcription factor associated with microphthalmia (MITF) in the onset of melanoma." (PMID 31336922, 2019). "We next wanted to identify if GH directly causes an upregulation in MITF expression and activity in melanoma." (PMID 31547367, 2019). "Across all melanoma lines tested, depletion of MITF was associated with a significant decrease in CDK7 transcription over time." (PMID 30651597, 2019). "In response to the dynamic intra‐tumor microenvironment, melanoma cells adopt distinct phenotypic states associated with differential expression of the microphthalmia‐associated transcription factor (MITF)." (PMID 31207090, 2019). "We combined immunostaining for PANX1, and the melanocytic-lineage marker to identify melanoma tumor cells, Microphthalmia/Melanogenesis-associated transcription factor (MITF) with sequentially sectioned biopsies staining using hematoxylin and eosin (H&E)." (PMID 30654593, 2019). "In agreement, targeting of FOXM1 and of EZH2, as well as of the upstream regulator c-Myc, induced a reversal of the EMT-like profile of melanoma cells, associated with upregulation of MITF and inhibited melanoma migratory and invasive activity." (PMID 30710146, 2019). "This is consistent with in vivo observations, where BRN2 is expressed in melanoma cells with low levels of MITF, a transcription factor associated with proliferation." (PMID 30804224, 2019). "Meanwhile, it has been reported in previous studies that MITF or loss of antigen expression conferred resistance to multiple targeted agents in melanoma." (PMID 31134073, 2019). "The significant reduction in melanin synthesis was mainly due to a dose-dependent inhibition of tyrosinase activity and protein expression associated with tyrosinase and melanocyte inducing transcription factor (MITF) in A375 melanoma cells." (PMID 31083417, 2019). "Much of melanoma biology is driven by the activity of the microphthalmia‐associated transcription factor MITF that promotes differentiation and proliferation, and whose expression is anti‐correlated with invasion and therapy resistance." (PMID 31207090, 2019). "The microphthalmia-associated transcription factor MITF plays a critical role in melanocyte development and in melanoma." (PMID 31881017, 2019). "Of note, the invasive/MITF-low signature is also associated with high expression of the NC-associated gene FOXD1 which was recently described to play a key role in melanoma migration and invasion via RAC1b regulation." (PMID 31118886, 2019). "By contrast, a subset of bulk melanomas (<20%) reveal a low abundance of MITF, which has been linked to an invasive, treatment-resistant phenotype." (PMID 30651597, 2019). "In the first such study, it was reported that a germline mutation in the human TF MITF that is associated with increased coincidence of melanoma and renal cancer also significantly reduces sumoylation of the protein." (PMID 30763307, 2019). "Here, resveratrol also downregulated melanogenesis-related proteins such as tyrosinase, tyrosinase related protein (TRYP) 1, TRYP2 and microphthalmia-associated transcription factor (MITF) in melanoma cells." (PMID 29522491, 2018). "Melanoma cells upregulate MITF expression to recover the loss of MAPK signaling upon exposure to MAPKi, enabling the cells to tolerate MAPKi." (PMID 29881716, 2018). "It has been shown that I3C promoted apoptosis in UVB-sensitized melanoma cells through the inhibition of Bcl-2 expression and down-regulation of microphthalmia-associated transcription factor (MITF)." (PMID 29565284, 2018). "Although this requires further investigation, MITF is involved in melanoma proliferation and survival and has been associated with DNA repair in melanoma." (PMID 29373959, 2018).
melanoma (continued). "The canonical Wnt signaling can co-operate with MAPK signaling to regulate the expression and activity of the master transcription regulator MITF, which is associated with melanoma cell proliferation." (PMID 30166456, 2018). "It is believed that MITF (microphthalmia-associated trancription factor), a key factor in melanoma transcription circuitry, maintains antiapoptosis in melanomas." (PMID 30201866, 2018). "Regulation of cell-type specific effectors downstream of TYRO3 has also been reported in specific tumor types, including Microphthalmia-associated transcription factor (MITF) in melanoma 48] and alpha-fetoprotein (AFP) in hepatocellular carcinoma." (PMID 30501104, 2018). "These drivers (i.e., MITF, c-Myc in melanoma) have been recently associated with clusters of non-coding regions on the genome called super enhancers that are usually marked with enhancer marks such as H3K4me1 as well as H3K27ac." (PMID 30466474, 2018). "PCR data showed that the microphthalmia-associated transcription factor (MITF), which is a lineage survival oncogene amplified in malignant melanoma cell lines, was expressed in MDA-MB-435 cells." (PMID 29636110, 2018). "The common master melanocyte transcription factor microphthalmia associated transcription factor (MITF) plays an important role in vertebrate melanoma formation." (PMID 30544544, 2018). "In melanoma, the proliferative and invasive states are defined by high and low microphthalmia-associated transcription factor (MITF) expression, respectively." (PMID 29881716, 2018). "Low MITF expression in melanomas has previously been linked to increased expression of RTKs such as AXL, EGFR, and PDGFRβ, which activate immediate–early signaling, causing resistance to RAF/MEK inhibitors." (PMID 28069687, 2017). "EZH2 and MITF, in fact, are targets of miR-101 and miR-137 that have been associated with the control of the invasive phenotype of melanoma cell lines." (PMID 29112174, 2017). "The inhibition of microphtalmia-associated transcription factor (MITF), a master regulator of melanocyte differentiation, increased the tumorigenic potential of melanoma cells, concomitantly with an upregulation of stem cell markers Oct4 and Nanog." (PMID 29156643, 2017). "It is interesting to notice that only when melanoma cells activate Notch signaling the MITF/miR-222/221 axis is deregulated and causes tumor invasion, further underlining how fundamental context and microenvironment are in regulation of tumor phenotype." (PMID 29112174, 2017). "Microphthalmia-associated transcription factor (MITF) plays a major role in the development and metastasis of melanoma, another highly malignant tumor." (PMID 29149895, 2017). "In the red tumor (caused by the CSE vector), we identified lentiviral integration in proximity of microphthalmia-associated transcription factor (MITF), a member of a family of transcription factors associated with melanoma development." (PMID 29383183, 2017). "Down-regulation of miR-137 in melanoma was strongly associated with MITF up-regulation, one of the most important gene involved with melanoma risk." (PMID 29126391, 2017). "Our data give new insight into the complex regulation of MITF, a key regulator of melanoma biology, and support previous findings that link metabolic disorders such as hyperglycemia and diabetes with increased melanoma risk." (PMID 28380427, 2017). "This study characterizes the tumor-suppressing effects of let-7a and miR-26a in malignant melanoma and identifies, for the first time, microphthalmia-associated transcription factor (MITF) as a novel gene target of miR-26a in malignant melanoma." (PMID 28698805, 2017). "MiR-340 was first reported in melanoma as a regulator of microphthalmia-associated transcription factor (MITF)." (PMID 28443990, 2017).
melanoma (continued). "Western blot analysis revealed that 10-HDA inhibited the activity of tyrosinase and the expression of tyrosinase-related protein 1 (TRP-1), TRP-2, and microphthalmia-associated transcription factor (MITF) in B16F1 melanoma cells." (PMID 28793915, 2017). "Another crucial player in phenotype switching in melanoma is the melanocyte-specifying microphthalmia-associated transcription factor (MITF), which controls a variety of target genes involved among others, in melanocyte differentiation." (PMID 29215016, 2017). "At the same time, the loss of MITF repression with the consequent induction of PGC1alpha and mitochondrial biogenesis force melanoma cells to switch back to oxidative phosphorylation." (PMID 28445987, 2017). "Gene expression profiling and experimental evidence indicate that during melanomagenesis, high levels of MITF in melanoma cells are associated with a vesicular trafficking signature hallmarked by high expression of Rab7, TBCD1D16, and Rab27a." (PMID 27896217, 2016). "Altogether, an inverse correlation was observed between ZEB1 and MITF levels in BRAFV600‐mutated melanoma at the intra‐tumoral level, and this ZEB1high/MITFlow profile showed a trend toward intrinsic resistance to MAPKi." (PMID 27596438, 2016). "Low MITF expression levels can be observed in invasive melanoma and are therefore associated with a low survival rate." (PMID 26927636, 2016). "In fact it has been shown that the hyper-activation of RAS-RAF-MEK-ERK signalling causes a significant reduction in MITF levels and therefore melanocytes and melanoma cells proliferation." (PMID 26863566, 2016). "Recent studies evidenced the correlation between CEACAM1 expressions in melanoma cell lines and melanoma tissue with microphthalmia-associated transcription factor (MITF)." (PMID 27642217, 2016). "We focused our work on the so-called master regulator of melanocytes and melanoma cells, microphthalmia-associated transcription factor (MITF)." (PMID 26927636, 2016). "One report showed that patients with SUMOylation-defective MITF germline mutation are predisposed to melanoma and RCC through activation of HIF-1α." (PMID 27741516, 2016). "The expression levels of MITF, encoding a basic helix–loop–helix/leucine zipper transcription factor, which is found mutated or amplified in 30–40% of melanoma’s, is dynamically altered during melanoma progression depending on the need." (PMID 27896217, 2016). "Oncogenes including BRAF and the microphthalmia-associated transcription factor (MITF) pathway play an important role in the pathogenesis of melanoma." (PMID 27845904, 2016). "The microphthalmia‐associated transcription factor (MITF) is the master regulator of melanocyte development, and MITF expression levels tightly regulate and control the phenotype of melanoma cells." (PMID 27596438, 2016). "Ganodermanondiol significantly inhibited tyrosinase activity, the expression of tyrosinase-related proteins, and microphthalmia-associated transcription factor (MITF) expression in B16F10 melanoma cells." (PMID 27801787, 2016). "This corresponds well to studies that directly implicated MITF in phenotype switching of melanoma cells." (PMID 26035829, 2015). "As previously discussed, high expression of MITF usually associates with a proliferative phenotype in melanoma." (PMID 25763355, 2015). "The melanocytic master regulator and melanoma oncogene microphthalmia-associated transcription factor (MITF) is another important melanoma player." (PMID 26000250, 2015).
melanoma (continued). "Both studies also reported that the melanoma differentiation marker microphthalmia-associated transcription factor (MITF) was regulated by the switch in ZEB expression." (PMID 25763355, 2015). "Highlighting its importance in the disease, amplification of MITF locus has been found in >15% of metastatic melanomas and germline mutations in MITF that predispose carriers to melanoma development have also been found." (PMID 25755924, 2015). "The finding of nuclear receptor half sites associated with MITF is unexpected as little is known about nuclear receptor function in melanoma although a therapeutic role of LXRb agonists has been demonstrated." (PMID 25803486, 2015). "Both phosphorylations promoting MITF degradation depend on melanoma-specific BRAFV600E causing the enhanced activation of MAPK (MAP kinase)/ERK1/2 pathway." (PMID 25433395, 2015). "In this review, we focus on melanoma-related mechanisms underlying the regulation of MITF expression and activity." (PMID 25433395, 2015). "Among gene products that operate downstream of the signal transduction BRAF–MEK–ERK pathway, the microphthalmia-associated transcription factor (MITF) seems to play the most relevant role in melanoma." (PMID 26322273, 2015). "While the entire depletion of MITF in melanoma cells can lead to cell cycle arrest and senescence, low MITF activity is associated with stem cell-like properties and invasiveness." (PMID 26000250, 2015). "MITF (microphthalmia-associated transcription factor) represents a melanocytic lineage-specific transcription factor whose role is profoundly extended in malignant melanoma." (PMID 25433395, 2015). "The first Principal Component of the basal transcriptomic analysis correlated with MITF expression, which has been implicated by several reports in drug resistance and oncogenesis in melanoma." (PMID 26405815, 2015). "An increased level of nuclear β-catenin positively regulates expression of CyclinD1 and MITF, which are associated with melanoma cell proliferation, survival and invasion." (PMID 26393652, 2015). "The MITF gene is amplified in ~20% of melanomas and MITF mutation can predispose to melanoma development." (PMID 25818589, 2015). "Germline mutations in additional genes were recently associated with melanoma occurrence: MITF, BAP1, TERT promoter, POT1, and MGMT." (PMID 26106605, 2015). "Coexistence of high MITF expression levels and BRAF mutations is able to transform human melanocytes; thus, MITF can function as a melanoma oncogene." (PMID 26322273, 2015). "Malignant melanoma is a neoplasm of melanocytes, and the microphthalmia‐associated transcription factor (MITF) is essential for the existence of melanocytes." (PMID 25818589, 2015). "Deubiquitinase USP13 (ubiquitin-specific protease 13) has been linked to the protection of MITF from proteasomal degradation in melanoma cells." (PMID 25433395, 2015). "For some time now, the ‘MITF rheostat’ model has linked levels of MITF ‘activity’ to distinct melanoma cell behaviours and phenotypes." (PMID 25818589, 2015). "In melanoma, AMPK was found to be an important regulator for the maintenance of MITF (Microphthalmia-associated transcription factor), a protein important for normal melanocyte development and differentiation that is associated with melanoma progression." (PMID 25812084, 2015). "Mutation-dependent alterations in MITF expression and activity have been found in a relatively small subset of melanomas." (PMID 25433395, 2015).
melanoma (continued). "A key determinant of melanoma differentiation sub-population identity is conferred by the expression and activation of microphthalmia-associated transcription factor (MITF)." (PMID 25051363, 2014). "Anti-senescence signaling is likely to take place in these cells because long-term depletion of MITF in melanoma cells triggers a senescence program associated with sustained growth arrest." (PMID 25538895, 2014). "In parallel with EMT-associated downregulation of certain melanoma antigens, particularly the differentiation antigens, which are under the control of MITF, we have also observed upregulation in expression of a number of cancer testis antigens (CTAg)." (PMID 25566505, 2014). "Overexpression of MITF desensitizes BRAF-mutated melanoma cells to BRAFi, but MITF expression can be impaired following treatment with histone deacetylase inhibitors (HDACi), suggesting the potential benefit of a combination strategy with MAPK inhibitors." (PMID 25344914, 2014). "The gradual loss of MITF protein expression was reflected by a decrease in the number of MITF-positive melanoma cells in the tumour, with the least number of MITF-positive cells observed in M3." (PMID 24399611, 2014). "This work led to the discovery of microphthalmia-associated transcription factor (MITF) as a lineage specific oncogenic transcription factor in melanoma." (PMID 24904423, 2014). "Primary melanoma specimens that exhibit a high nuclear ATF2:MITF ratio were found to be associated with metastatic disease and poor prognosis." (PMID 24743024, 2014). "An LFV in the melanocyte master regulator microphthalmia-associated transcription factor (MITF) increases melanoma risk (OR 2.19, 95% CI 1.41–3.45) and has a large effect in individuals with family history and multiple melanomas (OR 8.37, 95% CI 2.58–23.80)." (PMID 23982303, 2014). "Microphthalmia-associated transcription factor MITF is a lineage survival oncogene, amplified in 20% of melanoma cases; amplification of MITF is associated with a reduced 5-year survival." (PMID 24743024, 2014). "Compounds selected in the present study differentially altered the expression of melanocyte/melanoma specific microphthalmia-associated transcription factor (MITF) and proto-oncogene c-MYC." (PMID 24595456, 2014). "In this study, PRMT5 depletion was associated with decreased MITF in a majority of human melanoma cell lines." (PMID 24098663, 2013). "Transient overexpression of MITF in melanoma cells that are deficient in MITF (A375) but that express high levels of BRG1 activates ML-IAP expression." (PMID 23480510, 2013). "Microphthalmia-associated transcription factor (MITF), is thought to be a central player in melanoma biology, and it controls many aspects of the phenotypic expression of the melanocytic lineage." (PMID 24062982, 2013). "While MITF has only been considered for many years as the master regulator of melanocyte differentiation, more recent data have implicated MITF in the control of proliferation, survival, and the pathogeny of melanoma." (PMID 24416617, 2013). "Expression of MITF has been associated with proliferation and survival of melanoma cells via its target genes CDK2, Bcl-2, livin, c-met, and HIF1α." (PMID 23349796, 2013). "In this model, a transient decrease in MITF expression is associated with a melanoma-initiating cell phenotype, whereas moderate MITF level is linked with proliferation and high MITF level with differentiation." (PMID 24416617, 2013).